GXYLT1 (glucoside xylosyltransferase 1)
Description:
Glycosyltransferase which elongates the O-linked glucose attached to EGF-like repeats in the extracellular domain of Notch proteins by catalyzing the addition of xylose.
Synonyms: GLT8D3; FLJ43151
Tractability: Antibody: UniProt predicts a signal peptide or a membrane-spanning region. PROTAC: ubiquitination databases record sites on it; its protein half-life has been measured.
Gene: Protein-coding gene on chromosome 12 (42,081,845 to 42,144,874, reverse strand). Ensembl gene ENSG00000151233.
Subcellular location: Membrane
Subcellular location (Human Protein Atlas): Endoplasmic reticulum; Vesicles
Gene Ontology:
Molecular function: UDP-D-xylose:beta-D-glucoside alpha-1,3-D-xylosyltransferase activity; UDP-xylosyltransferase activity; glycosyltransferase activity
Biological process: protein O-linked glycosylation via glucose
Cellular component: membrane
Genetic constraint (gnomAD): Loss-of-function variants: 16 observed, 25.26 expected, observed/expected ratio (o/e) 0.63, 90% interval 0.43 to 0.96. The upper end of that interval is the gene's LOEUF score, 0.96, which puts it in group 4 of 6, group 1 being the genes least tolerant of losing a copy. Missense variants: 315 observed, 301.65 expected, observed/expected ratio (o/e) 1.04, 90% interval 0.95 to 1.15. Synonymous variants: 124 observed, 104.11 expected, observed/expected ratio (o/e) 1.19, 90% interval 1.03 to 1.38.
Homologues: Orthologues: chimpanzee GXYLT1 (99% identical), pig GXYLT1 (93% identical), dog GXYLT1 (92% identical), guinea pig GXYLT1 (92% identical), macaque YAF2 (87% identical), mouse Gxylt1 (86% identical), rat Gxylt1 (85% identical), rabbit GXYLT1 (77% identical), tropical clawed frog gxylt1 (71% identical), zebrafish gxylt1b (51% identical), Drosophila melanogaster shams (36% identical), Drosophila melanogaster CG9171 (13% identical), and 10 more. Paralogues in human: GXYLT2 (50% identical), LARGE1 (21% identical), LARGE2 (20% identical), XXYLT1 (16% identical), B4GAT1 (8% identical).
Diseases named in the same sentence as GXYLT1 in open-access papers:
GXYLT1 is named in the same sentence as 7 diseases in open-access papers, as found by Europe PMC text mining. Sharing a sentence is not in itself a finding about the gene and the disease. The quoted sentences say what the papers report.
sarcoma (1 paper, 2018). A usually aggressive malignant neoplasm of the soft tissue or bone. "Likewise, the undifferentiated pleomorphic sarcomas had different drug profiles but a mutation of the gene GXYLT1 was present in both." (PMID 29541442, 2018).
cancer (3 papers, 2017 to 2022). A tumor composed of atypical neoplastic, often pleomorphic cells that invade other tissues. "Our results identified GXYLT1 as a novel cancer-related gene with the ability to promote metastasis in CRC cells, and the stop-gain mutant GXYLT1S212* mainly enhanced metastasis through MAPK pathway activation." (PMID 35459861, 2022). "Among the two genes that have not been previously linked to cancer (GXYLT1 and RRP7A), GXYLT1 was recurrently mutated in 18 of 45 samples (40%)." (PMID 35459861, 2022). "Xylose modification of Notch by GXYLT1 and GXYLT2 suppresses Notch activity in Drosophila, whereas xylosylation by GXYLT2 upregulates the Notch pathway in human cancers." (PMID 35459861, 2022).
tumor (2 papers, 2017 to 2022). "Moreover, GXYLT1 mRNA levels gradually increased with tumor progression and differed significantly between tumor stages (p = 0.023, p < 0.001, and p = 0.056 for GSE17537, GSE33193, and GSE28702, respectively)." (PMID 35459861, 2022).
neuromuscular disease (1 paper, 2018). "Only two novel heterozygous missense mutations were identified in the LRP2 (low density lipoprotein-related protein 2) and GXYLT1 (glucoside xylosyltransferase 1) genes, which have no known roles in neuromuscular disease." (PMID 29879922, 2018).
GXYLT1 also shares sentences with these, for which no sentence is quoted: colorectal cancer (1 paper); diabetes (1); lung carcinoma (1).